PER2 (period circadian regulator 2)
Diseases named in the same sentence as PER2 in open-access papers (continued):
Sharing a sentence is not in itself a finding about the gene and the disease.
psychiatric disorder (3 papers, 2013 to 2022). A disorder characterized by behavioral and/or psychological abnormalities, often accompanied by physical symptoms. "Because PER2 is involved in several physiologically relevant pathways in addition to clock regulation, PER2 may mediate several biological functions that were previously linked to CDK5, such as the regulation of the brain reward system and psychiatric diseases." (PMID 31687929, 2019).
cardiovascular disease (2 papers, 2014). "Previous studies have shown that mutations of Per2 decrease the production of nitric oxide, vasodilatory prostaglandin(s), myocardial adaptation to ischaemia and mobilization of bone-marrow EPCs, all important to cardiovascular disease." (PMID 24621388, 2014). "Period 2 (Per2), one of the rhythm genes, plays an important role in cardiovascular disease." (PMID 24621388, 2014).
degenerative diseases (2 papers, 2021). "Our findings pave the way to future research on the implication of the PER2 gene on the neurobiological mechanism(s) underling cognitive reserve, as well as the neuropsychological functions in healthy and in cognitively impaired patients and in neurodegenerative diseases." (PMID 33919572, 2021). "These include Spon2, Adam19, Arntl, Cdkn1a, Cry2, Per2, Per3, Wee1, Rcan1, Slc41a3, Errfi1, and Bhlhe41, which are related to numerous cardiovascular and degenerative diseases of other organs as well as varying aging processes." (PMID 33668521, 2021).
neurological disorders (2 papers, 2017). "Of the genes annotated to the neuroactive ligand-receptor interaction pathway, a few were interesting for being associated to neurological disorders in other systems, for instance, the Period Circadian Clock 2 (PER2)." (PMID 28279172, 2017). "In this cohort, seven genes have already been associated with neurological disorders (MNX1, NINJ1, PER2, PHF20, PRSS56, RPH3A, and SBF1) in MalaCards and OMIM." (PMID 28769055, 2017).
colon polyp (1 paper, 2022). "per2 inactivation increased cell proliferation, β-catenin and D cyclin levels in HCT116 and SW480 cell lines and increased small intestinal and colon polyp numbers in Apc mutant mice." (PMID 36361993, 2022).
vascular disorder (1 paper, 2025). A general term used to describe any disease affecting blood vessels]. "Alterations of CLOCK, Bmal1, PER1, and PER2 has been observed in the placental cells of pregnant women with vascular disorders like pre-eclampsia." (PMID 40137423, 2025).
PER2 also shares sentences with these, for which no sentence is quoted: Sleep disturbance (3 papers); autism (2); brain glioma (2); brain tumors (2); colorectal tumor (2); endometrial carcinoma (2); Hodgkins lymphoma (2); sarcoma (2); -secreting pituitary adenoma (1); acute lymphocytic leukemia (1); adenocarcinoma (1); Angelman syndrome (1); ankylosing spondylitis (1); anxiety disorder (1); autosomal dominant disease (1); B cell lymphoma (1); brain injury (1); cardiomyopathy (1); cataract (1); diabetic retinopathy (1); dysthymia (1); endotoxemia (1); fibrosarcoma (1); genetic disorder (1); Hepatitis (1); Huntington disease (1); hyperandrogenism (1); hypersomnia (1); kidney disease (1); leiomyosarcoma (1).
A further 26 diseases each share a sentence with PER2 in 1 paper.